RN7SKP185 (RN7SK pseudogene 185)
Gene: Miscellaneous RNA gene on chromosome 20 (37,975,156 to 37,975,481, reverse strand). Ensembl gene ENSG00000199683.
Homologues: Orthologues: chimpanzee 7SK (98% identical), guinea pig 7SK (84% identical). Paralogues in human: 7SK (89% identical), RN7SKP48 (85% identical), RN7SKP227 (82% identical), RN7SKP118 (81% identical), RN7SKP62 (81% identical), RN7SKP174 (80% identical), RN7SKP187 (80% identical), RN7SKP178 (79% identical), RN7SKP76 (79% identical), RN7SKP292 (77% identical), RN7SKP160 (76% identical), RN7SKP55 (75% identical), and 284 more.
Diseases named in the same sentence as RN7SKP185 in open-access papers:
RN7SKP185 is named in the same sentence as 1 disease in open-access papers, as found by Europe PMC text mining. Sharing a sentence is not in itself a finding about the gene and the disease.
RN7SKP185 shares sentences with these, for which no sentence is quoted: cancer (1 paper).